IL6 (interleukin 6)
Diseases named in the same sentence as IL6 in open-access papers (continued):
Sharing a sentence is not in itself a finding about the gene and the disease.
Granuloma (continued). "Increased levels of IL-1, IL-6, IL-17, and IL-23 due to the upregulation of this cell population are described to play a central role in granuloma formation and maintenance in other granulomatous diseases of inflammatory or infectious origin, such as sarcoidosis and paracoccidioidomycosis." (PMID 38474383, 2024). "Granulomas, the hallmark pathology of chronic sarcoidosis, are composed primarily of macrophages derived from circulating blood monocytes, activated by pro-inflammatory cytokines including TNF and IL-6." (PMID 39284999, 2024). "However, the expression of IL-6 gene was upregulated significantly (P ˂ 0.01) in periapical abscess and granuloma but insignificantly in radicular cyst compared to healthy control." (PMID 34749700, 2021). "Here, our study indicates that the inhibition of IL-6 by genetic deletion or antibody neutralization promotes the progression of granuloma as well as the survival of mycobacteria in adult zebrafish infected with M. marinum or C3HeB/FeJ mice infected with H37Rv." (PMID 34608123, 2021). "Interestingly, deletion of the il6 gene increased the proportion of necrotic granulomas compared with that in WT zebrafish, suggesting a previously unidentified role of IL-6 in the inhibition of tuberculous granuloma necrosis." (PMID 34608123, 2021). "Instead, the appearance of MCs at incipient granulomas and surrounding mature granulomas suggests their contribution in orchestrating granuloma formation and maintenance potentially by the secretion of IL-17, IL-6, IL-8, MCP-1, IL-10, IFN-γ and IL-1β31,32." (PMID 34021178, 2021). "MWCNT entering the airways of mice have been shown to elicit several pro-inflammatory events that originate from their activation of the NLRP3 inflammasome and are associated with the induction of IL-6, TNF-α, and IL-1β, formation of granulomas and development of airway fibrosis." (PMID 29922162, 2018). "In granulomas, IL-4 expression was significantly higher than IL-6 (p=0.001) and TNF-α (p=0.001)." (PMID 29898177, 2018). "In corroboration, we showed that IL-6 deficiency in macrophages is associated with abrogated Th17 cell generation, diminished fungal load in the lungs, and absence of organized granulomas." (PMID 28871251, 2017). "Granuloma formation in giant cell arteritis (GCA), the other granulomatous large vessel vasculitis, has been clearly deciphered to involve the Th1 associated cytokines (IL-12, IFN-γ) as well as Th17 associated cytokines (IL-6, IL-17 and IL-23)." (PMID 28400869, 2017). "The authors suggested that suppression of TNFα and interleukin 1 (IL-1) and interleukin 6 (IL-6) by the nicotine in tobacco smoke may in turn suppress granuloma formation in the population studied." (PMID 26422615, 2015). "Urinary IL-6 may have been produced by inflammtory cells such as eosinophils or by uroepithelial cells in schistosome egg-driven granulomas in the urinary tract whereafter it can be found in urine." (PMID 25223302, 2014). "japonicum eggs induced a significant increase in the gene expression of the proinflammatory mediators MMP9, CCL2 (chemokine (C-C motif) ligand 2) and IL-6 (Interleukin 6), suggesting a potential role in the regulation of granuloma development via inflammatory cell recruitment and matrix remodelling." (PMID 23840855, 2013). "In addition, inflammaging may also be the reason for a higher presence of IL-6 in granulomas of elderly individuals in comparison with adult ones (p = 0.0019)." (PMID 35053012, 2021). "Elevated levels of IL-6 in the serum of HS patients have been described, and it has been suggested that IL-6 not only participates in the maintenance of inflammation but might also promote the formation of granulomas in lesions." (PMID 33182701, 2020). "Moreover, granulomas have the ability to secrete the inflammatory cytokines IL-6 and TNFα." (PMID 16542426, 2006). "In sarcoidosis granulomas, monocyte-derived macrophages are activated by pro-inflammatory cytokines including TNF and IL-6." (PMID 39284999, 2024).
Granuloma (continued). "The data revealed elevated expression of IL-1β, IL-6, and TNF-α, all known to reflect the pathogenesis of sarcoidosis, in the in vitro granuloma model." (PMID 38038136, 2023). "The presence of cytokines, to as IL-1β, IL-6 and TNF-a, suggest that these cytokines have a role in granuloma formation in to patients." (PMID 35672755, 2022). "The vaccinated and infected mice showed the increased expression of TNF-α, IFN-γ, and IL-6 following expression of the anti-inflammatory genes IL-10 and TGF-β in the liver, justifying the reduction in the number and size of the observed granulomas." (PMID 34992597, 2021). "M-CSF, Interleukin 6 (IL-6), and IFN-γ promote TGCs in many pathologic processes, such as xanthomas and granulomas." (PMID 32825443, 2020). "We observed that RNA expression of IL-7, IL17A, IL6, MARCO, IFN-γ, and IL-8 was significantly decreased in granulomas treated with α-MSH compared to the controls." (PMID 32350353, 2020). "Smoking is thought to trigger systemic increases in cytokines, such as IL-6, IL-1β, and TNF-α, which are critical in the formation of granulomas." (PMID 32872212, 2020). "Considering their crucial roles in fish inflammatory response, especially in the large yellow croaker, IL-6 and IL-1b may play important roles in the immune response of E. coioides to P. plecoglossicida during the process of white spot disease, and are closely related to the formation of granuloma." (PMID 31130962, 2019). "Increased levels of GSH in both RIF and RIF+NAC treated granulomas were accompanied by a notable increase in the production of IFN-γ and decreased levels of IL-6." (PMID 30258443, 2018). "In contrast with these results, we did not observe a significant decrease in M1 marker genes, including MMP9, NOS2, CCL2, IL-6 and ARG2, in granuloma FCMs compared with NFMs, although MMP13 and NF-κB1 levels, which are also M1-related genes, were decreased." (PMID 26197235, 2015). "In human livers with hepatic AE, the mRNAs of pro-inflammatory cytokines, interleukin (IL)-1β, IL-6, and TNF-α have been found in macrophages located at the periphery of granulomas, in those areas which were shown to be at the initiation of fibrogenesis." (PMID 23405141, 2013). "Not only was the expression of IL6 and TNF lower in late lesions, but it was confined to the outer edges of the generally circular granulomas." (PMID 20824205, 2010). "Moreover, in a granuloma animal model, using zebrafish embryos and larvae, PR3-driven granulomatous reactions were halted by IL-6 blocking, thus providing a rationale for novel therapeutic approaches." (PMID 38473038, 2024). "We also posit that the increasing expression of IL-6, IL-1β, IFN-γ and GM-CSF within silicotic individuals could be induced by early micro-granuloma development since it is a key mediator during acute phase response of silicosis." (PMID 36311760, 2022). "Accordingly, the conversion of acetyl-CoA to AcAcCoA by FadA reduces the cytoplasmic level of acetyl-CoA in host cells to suppress the histone H3K9 acetylation-mediated expression of Il6, a factor not previously known to inhibit granuloma pathology." (PMID 34608123, 2021). "IL-6 and TNF-α are pro-inflammatory cytokines which have a role in granuloma formation." (PMID 28859607, 2017). "However, LBR5, LBR6 and LBR8 induced increased levels of pro-inflammatory cytokines (IFN-γ, IL-2, IL-6, TNF-α and IL-17A), which are consistent with a robust Th1 immune response that especially promotes cellular proliferation and the formation of granulomas (IFN-γ and TNF-α)." (PMID 34046037, 2021). "Macrophages in the alveoli secrete a large number of interleukin-1 (IL-1), interleukin-6 (IL-6), tumor necrosis factor-α (TNF-α), and other cytokines, so that lymphocytes and monocytes are accumulated in mycobacterial invasion sites and followed by granulomas formation." (PMID 31921874, 2019).
Granuloma (continued). "Mice infected with a strain of M. tuberculosis disrupted in the mce1 operon are unable to mount a strong pro-inflammatory response against WT Mtb, as evidenced by decreased levels of IL-6 and TNF-α; consequently, these animals do not form organized granulomas." (PMID 32973761, 2020).
Salmonella Infections (78 papers, 2009 to 2026). Infections with bacteria of the genus SALMONELLA. "Despite unchanged basal iron metabolism in the spleen and liver, iron regulatory proteins and the interleukin (IL)-6-hepcidin axis are altered in Nr2f6-deficient mice during Salmonella infection, reducing hypoferremia." (PMID 40605423, 2025). "The IL-6 levels in the ileum were upregulated by the Salmonella infection, but suppression by the previous association with BB12 resulted in a non-significant increase against the control GF group." (PMID 36768650, 2023). "A previous study conducted by our group found that CB reduced the elevation of IL-1 and IL-6 caused by Salmonella infection in broilers." (PMID 36674973, 2023). "Salmonella infection changes the gut barrier and immune system by causing the production of cytokines such as interleukin-1 (IL-1β), interleukin-8 (IL-8), interleukin-6 (IL-6), lipopolysaccharide-induced tumor necrosis factor (LITAF), and interferon-(IFN-γ)." (PMID 34944274, 2021). "VDR-null mice have increased IL-6 production after Salmonella infection and VDR deletion is associated with elevated NF-κB in intestinal epithelia." (PMID 23240054, 2012). "Interleukin 6 is a common pleiotropic cytokine associated with Salmonella infection." (PMID 38465263, 2024). "(C–E) RT-qPCR analysis of mRNAs encoding inflammatory cytokines (Tnfα, Il1β, and Il6), chemokines (Ccr2, Ccl2, Cxcl1, and Cxcl10) and macrophage biomarkers (Nos2 and Arg1) in BMDMs measured at the indicated times after Salmonella infection (multiplicity of infection [MOI] = 1) (n = 5)." (PMID 39475776, 2024). "Salmonella infection in chickens can cause mild enteric inflammation characterized by increased mRNA expression of proinflammatory cytokines including interleukin-6 (IL-6), IL-8, IL-12, LPS-induced tumor necrosis alpha factor (LITAF), and interferon gamma (IFN-γ)." (PMID 29706903, 2018). "Knowledge of asymptomatic Salmonella infection and latent carriers is limited, but it is well known that LPS causing symptoms of disease can induce an acute phase reaction in humans and animals and release pro-inflammatory cytokines such as interleukin-6 (IL-6) and tumour necrosis factor α (TNF-α)." (PMID 30360353, 2018). "Concomitantly, we investigated the regulatory effect of EcN preconditioning on the release level of tumor necrosis factor alpha (TNF-α)and interleukin-6 (IL-6) in host cells induced by Salmonella infection." (PMID 41181117, 2025). "Consistent with our result showing IL-6 peak at day 14 post-challenge, reflects the acute inflammatory response to systemic Salmonella infection." (PMID 41242154, 2025). "The Salmonella infection significantly altered mRNA levels of pro-inflammatory cytokines (IL-6, IL-1α, IL-1β, and TNF-α)." (PMID 38667028, 2024). "Salmonella infection triggers the release of cytokines such as IL-6, IL-1β and TNF-α, resulting in systemic inflammatory stress." (PMID 38715123, 2024). "PJ-34 exerted protective effects on intestinal epithelial cells against invasive Salmonella infection by upregulating Il6 expression through the ERK and NF-κB signaling pathways." (PMID 39560359, 2024). "Salmonella infection in chickens increases the serum concentrations of IgG and IgA and IL-1β, IL-6, and TNF-α." (PMID 38053560, 2023). "Salmonella infection significantly increased the ileal contents of inflammatory cytokines (IL-1β, IL-6, IL-8, TNF-α, IFN-β and IFN-γ) compared with the CON." (PMID 36670458, 2023). "Salmonella infection increased the expression of IL-1β, IL-6, and TNF-α in the jejunal and ileal mucosa of broilers." (PMID 38053560, 2023). "In the intestine, enterocytes produce IL-6 with anti-inflammatory and cell-protective properties that strengthen the intestinal barrier and can alleviate its disruption by Salmonella infection." (PMID 38003758, 2023). "The previous colonization with RP37 alleviated damage of the ileum caused by the Salmonella infection, and RP37 and LA downregulated plasmatic levels of IL-6." (PMID 38003758, 2023).
Salmonella Infections (continued). "Let-7 can be downregulated to induce the release of cytokines IL-6 and IL-10 to participate in the regulation of the immune response to Salmonella infection in macrophages." (PMID 35222370, 2022). "Salmonella infection can lead to mild intestinal inflammation, which releases cytokines and other factors like interleukin-6 (IL-6), IL-8, IL-12, LPS-induced tumor necrosis factor alpha (LITAF) and interferon gamma (IFN-γ)." (PMID 36311708, 2022). "We show that NF-κB and its downstream targets (such as iNos, Il-6 and Tnf-α) typically induced during Salmonella infection, are suppressed during fasting." (PMID 34352037, 2021). "Evidence suggests that IL-6 secretion is a crucial factor in broiler chickens that confers protection against Salmonella infection." (PMID 34061266, 2021). "In contrast, compared to the levels seen upon wild-type Salmonella infection, we detected markedly reduced levels of both IL-6 and IL-8 upon infection with the ΔSPI1/2 strain." (PMID 32071273, 2020). "It has also been reported that Salmonella infection increased the levels of IL-6, IL-8, and IL-1β in the colons of pigs." (PMID 32150574, 2020). "Cytokine IL-6 is indicative of the initiation of an acute phase response occurring in avian cells in response to Salmonella infection." (PMID 32054193, 2020). "It is likely that when gut-resident Mφ fail to contain the Salmonella infection they release cytokines/chemokines (e. g., IL-6, IL-8, TNF-α, and CCL3) to attract more macrophages and PMN to the diseased area." (PMID 31412039, 2019). "Next, we analyzed activation of endogenous interleukin 6 (IL-6), an NF-κB-regulated cytokine, during Salmonella infection." (PMID 28069818, 2017). "The multifunctional cytokine IL-6 has also been shown to confer a protective effect at the mucosal level against invasive Salmonella infection." (PMID 28143524, 2017). "As studied in mice infection model, the mechanisms employed by IFN-γ, IL-2 and IL-6 for establishing protection against Salmonella infection are diverse in nature." (PMID 28143524, 2017). "Upregulation in IL-6 levels can trigger the rapid development of a cytotoxic T cell response against Salmonella infection in mice." (PMID 28143524, 2017). "Ripk3-/-Casp8-/- BMDMs showed dramatically reduced IL-6 and IL-12p40 production compared with B6 or Ripk3-/- cells in response to Yersinia and Salmonella infection." (PMID 27737018, 2016). "The ELISA is sensitive enough to detect IL‐6 protein in the culture medium 1 h post Salmonella infection." (PMID 25214524, 2014). "Early during Salmonella infection, immune cells including macrophages, granulocytes and lymphocytes are central to control bacterial replication by producing IL-6, TNF, IFN-γ and IL-12." (PMID 24505352, 2014). "Compared to uninfected mice, Salmonella infection induces increased IL-6 responsiveness in naïve CD4 T cells but this responsiveness varied with the levels of fecal shedding." (PMID 23754944, 2013). "Intestinal IL-6 production is induced by Salmonella infection and is likely to drive Salmonella-specific differentiation towards a Th17 lineage in the intestine." (PMID 22275869, 2012). "Effector activation of STAT3 may at first seem counterintuitive, as the host is already producing IL-6 in response to Salmonella infection, and we previously observed activation of STAT3 in infected mice even in the absence of SarA." (PMID 40188438, 2025). "Therefore, when the intestinal barrier function is destroyed upon salmonella infection, these pro-inflammatory cytokines, including IL-1β, IL-6, IL-8, IFN, and TNF-α, are activated." (PMID 35371085, 2022). "Additionally, Clock deficient BMDMs exhibit reduced expression of proinflammatory genes Il-6, Il1b, Tnfα, Ifn-β, and Ccl2 upon LPS stimulation and decreased secretion of IL-6 and IL-1β after Salmonella infection." (PMID 34595127, 2021).